AGPAT3 (1-acylglycerol-3-phosphate O-acyltransferase 3)
Description:
Converts 1-acyl-sn-glycerol-3-phosphate (lysophosphatidic acid or LPA) into 1,2-diacyl-sn-glycerol-3-phosphate (phosphatidic acid or PA) by incorporating an acyl moiety at the sn-2 position of the glycerol backbone. Acts on LPA containing saturated or unsaturated fatty acids C16:0-C20:4 at the sn-1 position using C18:1, C20:4 or C18:2-CoA as the acyl donor. Also acts on lysophosphatidylcholine, lysophosphatidylinositol and lysophosphatidylserine using C18:1 or C20:4-CoA. Has a preference for arachidonoyl-CoA as a donor (By similarity). Also has a modest lysophosphatidylinositol acyltransferase (LPIAT) activity, converts lysophosphatidylinositol (LPI) into phosphatidylinositol (By similarity).
Synonyms: 1-AGPAT 3; LPAAT-gamma; LPAAT3; LPLAT3; LPAAT-GAMMA1
Tractability: Antibody: UniProt predicts a signal peptide or a membrane-spanning region. PROTAC: ubiquitination databases record sites on it; its protein half-life has been measured.
Gene: Protein-coding gene on chromosome 21 (43,865,223 to 43,987,592, forward strand). Ensembl gene ENSG00000160216.
Subcellular location: Endoplasmic reticulum membrane; Nucleus envelope
Pathways (Reactome):
Metabolism: Synthesis of PA
Vesicle-mediated transport: COPI-independent Golgi-to-ER retrograde traffic
Gene Ontology:
Molecular function: 1-acylglycerol-3-phosphate O-acyltransferase activity; protein binding; 1-acylglycerophosphocholine O-acyltransferase activity; 1-acylglycerophosphoserine O-acyltransferase activity; acyltransferase activity; lysophosphatidic acid acyltransferase activity
Biological process: phosphatidic acid biosynthetic process; phospholipid biosynthetic process; CDP-diacylglycerol biosynthetic process; glycerophospholipid metabolic process
Cellular component: endoplasmic reticulum; endoplasmic reticulum membrane; membrane; nuclear envelope; plasma membrane; Golgi membrane
Genetic constraint (gnomAD): Loss-of-function variants: 5 observed, 50.04 expected, observed/expected ratio (o/e) 0.0999, 90% interval 0.051 to 0.21. The upper end of that interval is the gene's LOEUF score, 0.21, which puts it in group 1 of 6, group 1 being the genes least tolerant of losing a copy. Missense variants: 315 observed, 510.28 expected, observed/expected ratio (o/e) 0.62, 90% interval 0.56 to 0.68. Synonymous variants: 212 observed, 214.88 expected, observed/expected ratio (o/e) 0.99, 90% interval 0.88 to 1.11.
Homologues: Orthologues: chimpanzee AGPAT3 (99% identical), macaque AGPAT3 (99% identical), dog AGPAT3 (93% identical), mouse Agpat3 (92% identical), guinea pig AGPAT3 (92% identical), rat Agpat3 (92% identical), pig AGPAT3 (87% identical), tropical clawed frog agpat3 (81% identical), zebrafish agpat3 (75% identical), Drosophila melanogaster Agpat3 (40% identical), Drosophila melanogaster Agpat4 (36% identical). Paralogues in human: AGPAT4 (61% identical), LCLAT1 (26% identical), AGPAT5 (21% identical), LPGAT1 (20% identical).
Diseases named in the same sentence as AGPAT3 in open-access papers:
AGPAT3 is named in the same sentence as 20 diseases in open-access papers, as found by Europe PMC text mining. Sharing a sentence is not in itself a finding about the gene and the disease. The quoted sentences say what the papers report.
breast carcinoma (2 papers, 2018 to 2024). "The EEC genes identified in here (with the exception of AGPAT3/4, ASTN2, and EEA1), have previously been shown to be associated with breast cancer in gene expression and functional studies." (PMID 29965997, 2018).
arterial disorder (1 paper, 2023). An impairment of the structure or function of the blood vessels which carry blood away from the heart. "Those SNPs located at RDH5/ORMLD2 and AGPAT3 genes also have a strong effect on multiple ocular traits and diseases (such as macular thickness and retinal detachment), hypertension, and arterial disorders." (PMID 37188768, 2023).
osteosarcoma (1 paper, 2025). A usually aggressive malignant bone-forming mesenchymal neoplasm, predominantly affecting adolescents and young adults. "Our study highlights a strong correlation between glycerolipid metabolism and osteosarcoma prognosis, identifying AGPAT3 and ALDH7A1 as key genes associated with patient outcomes." (PMID 41502512, 2025). "To illustrate the function of AGPAT3 in the osteosarcoma immune microenvironment, we used single-cell analysis." (PMID 41502512, 2025). "To further explore the role of essential prognostic genes of glycerolipid metabolism in osteosarcoma immune microenvironment, we grouped the cohort based on the expression of AGPAT3." (PMID 41502512, 2025). "The development of AGPAT3-related agents deserves further study to explore their potential in enhancing the therapeutic effect of osteosarcoma." (PMID 41502512, 2025). "AGPAT3 emerges as a critical gene with the lowest hazard ratio, positioning it as a promising therapeutic target in osteosarcoma." (PMID 41502512, 2025). "These clinical studies have provided novel insights into the role of AGPAT3 in the osteosarcoma immune microenvironment and identified it as a potential target to enhance immunotherapy outcomes." (PMID 41502512, 2025). "This study demonstrated the correlation between AGPAT3 and osteosarcoma prognosis and identified the potential LAPR6 inhibitors." (PMID 41502512, 2025). "Knockdown of AGPAT3 in osteosarcoma cells resulted in elevated lysophosphatidic acid (LPA) levels, which regulated the immune environment, inhibiting cytotoxic T cell function through TAMs’ LPAR6 signaling." (PMID 41502512, 2025). "Glycerolipid metabolism-related genes 1-acylglycerol-3-phosphate O-acyltransferase 3 (AGPAT3) and aldehyde dehydrogenase 7 family member A1 (ALDH7A1) were identified as key prognostic genes in osteosarcoma, with high AGPAT3 expression correlating with improved survival." (PMID 41502512, 2025). "To further examine whether LPA synthesis mediated by osteosarcoma-derived AGPAT3 induces cytokine secretion through LPAR6, we treated THP-1-derived macrophages with XAA, an LPAR6 inhibitor, followed by co-culture experiments." (PMID 41502512, 2025). "AGPAT3 is an important gene related to the prognosis of osteosarcoma." (PMID 41502512, 2025). "Furthermore, AGPAT3 knockdown in osteosarcoma cell lines, combined with co-culture experiments, confirmed that LPA regulates TAM-mediated secretion of IL-10 and IL-6 via the LPAR6 signaling pathway." (PMID 41502512, 2025). "These cell communication results showed that low AGPAT3 expression in osteosarcoma may lead to elevated LPA levels." (PMID 41502512, 2025). "In osteosarcoma, the combination of AGPAT3 or ALDH7A1 may be used to predict the prognosis." (PMID 41502512, 2025). "AGPAT3 is shown to bridge LPA and PA metabolism with the tumor immune microenvironment, offering novel insights into their roles in osteosarcoma progression." (PMID 41502512, 2025). "We found that low expression of AGPAT3 and ALDH7A1 is significantly correlated with poor prognosis in osteosarcoma patients." (PMID 41502512, 2025). "To explore whether AGPAT3 and LPA influence TAM functionality, we knocked down AGPAT3 (AGPAT3-KD) in the osteosarcoma cell line 143B." (PMID 41502512, 2025). "Genes AGPAT3 and ALDH7A1 in the glycerolipid metabolic pathway may serve as prognostic markers and play key roles in osteosarcoma." (PMID 41502512, 2025). "Analysis of the osteosarcoma immune microenvironment suggests that AGPAT3 may not regulate the immune microenvironment by influencing the number or proportion of immune cells." (PMID 41502512, 2025).
ovarian carcinoma (1 paper, 2025). A malignant neoplasm originating from the surface ovarian epithelium. "Overall, our findings suggest that AGPAT3 enhances cisplatin resistance in ovarian cancer through mTORC1 induction." (PMID 40063560, 2025). "Therefore, to identify genes involved in cisplatin resistance in ovarian cancer, RNA-seq analysis of A2780cp (cisplatin-resistant) and A2780 (cisplatin-sensitive) cell lines was performed, revealing 1-acylglycerol-3-phosphate O-acyltransferase 3 (AGPAT3) as a differentially expressed candidate gene." (PMID 40063560, 2025). "Therefore, downregulating AGPAT3 expression or blocking its enzymatic product, phosphatidic acid, from binding to mTOR might be considered therapeutic approaches to overcome cisplatin chemoresistance in ovarian cancer, which has fewer side effects than other classes of mTOR inhibitors do." (PMID 40063560, 2025).
Stroke (1 paper, 2025). Sudden impairment of blood flow to a part of the brain due to occlusion or rupture of an artery to the brain. "Even though lipid metabolism is known to be profoundly affected by ischemia, the specific role of AGPAT3 in stroke remains unexplored." (PMID 41342963, 2025).
virus infection (1 paper, 2023). "The top 4 were “Cell matrix adhesion and organization” (COL6A1, COL6A2, COL18A1, JAM2, ADAMTS5 and POFUT2), “Immune/virus infection response” (MX1 and MX2), “Histone modification and chromatin remodeling” (NRIP1) and “Glycerolipid and lipid metabolism” (AGPAT3)." (PMID 38095646, 2023).
tumor (6 papers, 2021 to 2026). "Single-cell analysis revealed that AGPAT3 expression is associated with tumor immune microenvironment, particularly with TAMs." (PMID 41502512, 2025). "AGPAT3 is closely linked to the regulation of the tumor immune microenvironment." (PMID 41502512, 2025). "In summary, low expression of AGPAT3 in tumor cells facilitated the accumulation of LPA, which promoted the IL-6 and IL-10 expression of TAMs through LAPR signaling." (PMID 41502512, 2025). "In this study, AGPS and AGPAT3 were found to be expressed at higher levels in GC tissues, especially in CagA+ H. pylori-infected tumor tissues, than in normal tissues." (PMID 38383581, 2024). "Previous reports have demonstrated that the phosphatidic acid acyltransferase 1-acylglycerol-3-phosphate O-acyltransferase 3 (AGPAT3) regulates lipid metabolism and ferroptosis, which could influence the survival of tumor cells." (PMID 41502512, 2025). "This profile of genes includes AGPAT3, AKR1B1, PLD1, and UGT8, all of which have previously been reported to be involved in tumor proliferation." (PMID 34568042, 2021).
cancer (4 papers, 2024 to 2025). A tumor composed of atypical neoplastic, often pleomorphic cells that invade other tissues. "Our study also highlights the important role of the MEK/ERK/SRF pathway in driving ferroptosis sensitivity and regulating the expression of AGPS and AGPAT3 in cancers." (PMID 38383581, 2024). "However, whether AGPAT3 is also involved in other chemoresistance systems and in other cancer types remains to be tested." (PMID 40063560, 2025).
AGPAT3 also shares sentences with these, for which no sentence is quoted: Obesity (3 papers); male infertility (2); and heart disorders (1); hyperlipidemia (1); Hypertension (1); infection (1); infertile (1); lipodystrophy (1); malaria (1); ovarian endometrioid carcinoma (1); retinal degeneration (1); retinal detachment (1).